MIR4282 (microRNA 4282)
Synonyms: hsa-mir-4282
Gene: MicroRNA gene on chromosome 6 (72,967,687 to 72,967,753, reverse strand). Ensembl gene ENSG00000266180.
Homologues: Orthologues: chimpanzee MIR4282 (100% identical), macaque MIR4282 (100% identical).